FOXO1 (forkhead box O1)
Diseases named in the same sentence as FOXO1 in open-access papers (continued):
Sharing a sentence is not in itself a finding about the gene and the disease.
cancer (continued). "Therefore, it is plausible that FOXO1 and FADD have synergistic or antagonistic effects on cell cycle regulation and the response to anticancer drug treatment in cancer cells." (PMID 41596582, 2026). "However, in cancer cells, SIRT1 reprograms FOXO1 via site-specific deacetylation of lysine residues (e.g., K242, K245, and K262)." (PMID 41008982, 2025). "miR-142-3p targets the tumor suppressor FOXO1, promoting proliferation, and miR-4449 may influence STAT3 signaling by targeting SOCS3, as suggested in other cancers." (PMID 41462933, 2025). "Moreover, newly discovered small molecules inhibitor of FOXO1 and FOXM1 have shown efficacy in preclinical cancer models, demonstrating the feasibility of targeting FOX transcription factors in vivo as well." (PMID 39777582, 2025). "Among these, FOXO1 and FOXO3 are the most well-studied in the context of cancer." (PMID 38994962, 2024). "MiR-21 also plays an oncogenic role in other cancers by targeting the forkhead box O1 (FOXO1), protein tyrosine phosphatase non-receptor type 14 (PTPN14), and PTEN." (PMID 38559560, 2024). "Studies report that TCF19 could promote cell proliferation and contribute to the malignant progression of cancer through mechanisms such as regulating WWC1, inhibiting FOXO1, or activating the ATK/FOXO1 signalling pathway." (PMID 38579171, 2024). "In addition, HLF and ARID5B were identified as TFs of Tregs in precancer stages (e.g., N_HPV, AAH, NEOLP, EOLP), while regulons such as FOXO1 and STAT5B were specifically detected in cancers (e.g., IDC, AIS, MIAC, IAC and PDAC)." (PMID 38645221, 2024). "Interestingly, phosphorylation of FoxO1 has also been shown to increase HIF-1 and VEGF expression and promote angiogenesis in some cancer models, further implicating its involvement in endothelial cell function." (PMID 38510106, 2024). "Forkhead Box O1 (FOXO1) has been reported to play important roles in many tumors.However, FOXO1 has not been studied in pan-cancer." (PMID 38716982, 2024). "We then examined the correlation between the expression of FOXO1 and DSS invarious types of cancer." (PMID 38716982, 2024). "The transcriptional activity of the protein tyrosine phosphatase non-receptor type 22 (PTPN22) gene increased in all stages of the cancer, but the p-value was only less than 0.05 in CSIV vs. C. Forkhead box O1 (FOXO 1) and ubiquitin B (UBB) are statistically overexpressed in CSI." (PMID 38002011, 2023). "Furthermore, activation of FOXO1 or FOXO3a, members of the FOXO family, can lead to chemoresistance in certain cancers." (PMID 38125769, 2023). "In addition, FOXO1, an upstream transcription factor of SOX2, participating in cancer stemness had been identified to participate in paclitaxel resistance in OC." (PMID 38143770, 2023). "Importantly, endogenous FOXO1 activity correlated with CAR T and TIL responses in patients, underscoring its clinical relevance in cancer immunotherapy." (PMID 37986944, 2023). "Our study identified for the first time the existence of miR-9-5p/FOXO1/CPEB3 FFL and revealed its regulatory role in HCC progression, which may represent a new potential target for cancer therapy." (PMID 35805200, 2022). "Finally, APDT led to up-regulation of developmental transcription factors involved in stem cells and cancer stem cells (ETV4, SOX9, FOXO1 and FOXO3)." (PMID 35328625, 2022). "Many previous studies have reported the cancer‐promoting potential of USP22, including the induction of cell proliferation and DNA repair, activation of c‐Myc/NAMPT/SIRT1‐dependent FOXO1 and YAP signaling, and deubiquitination of CD274 to suppress anticancer immunity." (PMID 34743406, 2022). "Since SKP2 degrades FOXO1 upon methylation by G9a, targeting SKP2 activity may enhance FOXO1 activity despite increased G9a activity in cancers." (PMID 35740522, 2022).
cancer (continued). "There were eight favorable prognostic genes and six poor prognostic genes incorporated in this signature, and a variety of OSRGs such as CD38, FOXO1, HGF, IL18BP, and TRPM2 were closely involved in the previous studies regarding cancer subtypes and immune landscape." (PMID 36561981, 2022). "By integrating patterns of FOX genes expression with anticancer drugs sensitivity, we speculated that six FOX genes, including FOXO3, FOXO1, FOXN3, FOXK2, FOXN2, and FOXJ3, might be important for the development and treatment of a wide range of cancers." (PMID 36292640, 2022). "Here, we evaluated the expression, prognostic value, mutation, methylation, and clinical features of four FOXO family genes (FOXO1, FOXO3, FOXO4, and FOXO6) in 33 types of cancers based on the Cancer Genome Atlas (TCGA) and Genotype Tissue Expression (GTEx) databases." (PMID 36555288, 2022). "Conversely, maintained action of Foxo1 was reported to protect against the disruption of lipid metabolism characteristic of cancer, and this was the case in our hSDC1+/+ DEN tumors where, in contrast to the WT DEN tumors, expression of Foxo1 remained unaltered compared to untreated controls." (PMID 33801718, 2021). "Similarly, miR-182 suppresses both FOXO1 and FOXO3 expression levels in prostate and skin cancer, respectively, to promote cancer cell migration and invasion." (PMID 32372224, 2020). "Previously, a distinct function of FOXO1 in HDI-mediated autophagy in human cancer cells was reported, suggesting the possibility of a novel therapeutic strategy by combining HDIs and autophagy inhibitors in cancer therapy." (PMID 32929346, 2020). "The KDM3A and Ets1 upregulated transcriptomes, alone and together, also contain numerous additional genes implicated in cancer promotion, which are not dependent on PAX3/FOXO1 for expression." (PMID 32697014, 2020). "Furthermore, PERK has previously been shown to promote FOXO1 activity by direct phosphorylation at Ser298, Ser301 and Ser303, representing another layer of FOXO regulation in cancer." (PMID 32372224, 2020). "In addition, FOXO proteins (FOXO1, FOXO3 and FOXO4) are putative targets for prevention cancer therapy-related drug resistance." (PMID 31450545, 2019). "Together with FOXO3 activation, FOXO1 overexpression via miRNA interactions is involved in upregulation of ABCB1 gene, coding for P-glycoprotein, well known responsible for decreased drug accumulation in multidrug-resistant cancer cells." (PMID 31234353, 2019). "Moreover, deletion of FOXO1, FOXO3, and FOXO4 in mice results in a cancer-prone phenotype with development of thymic lymphomas and hemangiomas." (PMID 30646603, 2019). "FOXOs, comprising FOXO1, FOXO3, FOXO4, and FOXO6, are the focus of cancer research recently." (PMID 30046342, 2018). "In addition, accumulated evidence also supports a role of FOXO1 and HBP1 in metastatic potential of cancer cells." (PMID 28099936, 2017). "Among them were CEBPA and CEBPB (cell cycle regulation), RELA and CREL (NF-κB pathway), TCF7L1 (Wnt/β-catenin signaling pathway), SMAD3 [transforming growth factor beta (TGF-β) signaling], FOXO1 and NFAT, all of which are involved in cancer initiation and progression." (PMID 28344555, 2017). "Multiple miRNAs regulate PTEN, FOXO1 and SMAD2, resulting in cancer progression." (PMID 29069829, 2017). "It will be critical to determine whether NFIL3 is required in DLBCLs that contain activated FOXO1 and the MLL-AF9 cancers in order to block the activation of cell death by FOXO factors." (PMID 26539561, 2014). "Deregulation of FOXO1 and FOXP1 had been shown in many cancer types." (PMID 21655267, 2011). "DIM-3,5-Cl2 acts as an inverse NR4A1 agonist in cancer cells, and inRh30 cells, induction of proliferation by PFOS is inhibited by DIM-3,5-Cl2.Moreover, DIM-3,5-Cl2 also inhibits PFOS-induced NR4A1-regulatedPAX3-FOXO1 (FOXO1) and G9a gene products in Rh30 cells." (PMID 40066943, 2025).
cancer (continued). "Nevertheless, whether arzanol’s SIRT1 inhibition contributes to its anticancer effects requires cancer cell-specific studies examining SIRT1 and FOXO1 expression and activity following arzanol treatment, complemented measuring SIRT1 overexpression or comparison with selective SIRT1 inhibitors." (PMID 41304625, 2025). "Theinvestigation of FOXO1 expression and functions in pan-cancer has not been conductedbefore." (PMID 38716982, 2024). "Functional enrichment analysis and gene set enrichment analysisshowed that FOXO1 might play roles in tumors through immunoregulatoryinteractions between a lymphoid and a non-lymphoid cell, TGF-beta signalingpathway, and transcriptional misregulation in cancer." (PMID 38716982, 2024). "This was accompanied by increased expression of FOXO1 and p21 in all cancer cell lines except T24, which may explain the lack of increase in caspase 3/7 activation in T24 by the combination of 20 and cisplatin." (PMID 39409994, 2024). "Furthermore, the upregulation of FOXO1 affects the malignancy of various cancers, including non-small-cell lung cancer (NSCLC)." (PMID 38338691, 2024). "In addition, of all the 31 Onco/TSGs harboured sHyperMethyl and sHypoMethyl in their gene body, 7 genes (HOXD11, TAL1, HOXA9, PAX5, FOXP1, FOXO1, TERT) were reported to serve as potential DNA methylation-based biomarkers for non-invasive early cancer diagnosis." (PMID 37393582, 2023). "Contrary to knocking down hsa_circRNA_0040462, CAP significantly suppressed FOXO1 (p=1E-2) and KI67 (p=1.04E-6), where KI67 expression reduced to 40% of its original level, suggesting the consistent regulatory direction of CAP and hsa_circRNA_0040462 in cancer cell proliferation." (PMID 35582416, 2022). "The two phosphosites of FOXO1 found in this study are important for follicular development, prevent GCs from apoptosis, and may be valuable for developing compounds that disrupt the phosphorylation of FOXO1 by DYRK1A, which could serve as a potential choice for cancer-related drug design." (PMID 33520998, 2020). "Our previous study showed that FOXO1-negative cells carry cancer stem-like characteristics in PDAC." (PMID 31027497, 2019). "However, activation of the UPP and ALP in the muscle of cancer hosts does not appear to require the PI3K-Akt-FoxO1/3 signaling pathway." (PMID 31480237, 2019). "Collectively, our findings of a significant decrease in the expression levels of FOXO1 and miR-30d-5p in the PTC compared to normal adjacent tissues suggest that the PTC cells may tend to preserve their autophagy activity by considering the role of autophagy in the cancer cell homeostasis." (PMID 36777002, 2022). "In addition, members of the FOXO family, such as FOXO1, FOXO3, FOXO4, and FOXO6, have been found to participate in various physiological responses, such as DNA damage, caloric restriction and oxidative stress, and play crucial roles in cancer initiation, progression, and chemo‐resistance." (PMID 32368828, 2020). "Therefore, FoxO1 might not only play an important role in the maintenance of the CSC pool but also mediate the formation of a unique vascular niche for the maintenance and self-renewal of CSCs in cancers, including pNETs." (PMID 31739580, 2019). "Notably, cytoplasmic FOXO1, which is likely to be inactive and should have no affect on expression of target genes in stress response, was strongly expressed in resistant cells both in cancer cell lines and clinical samples." (PMID 18319717, 2008). "For instance: FOXO1 is downregulated in CML but shows no significant change in AML or CLL, unlike previous pan-cancer autophagy markers (e.g., BECN1) that lack disease specificity." (PMID 40503228, 2025).
cancer (continued). "Future mechanistic studies are warranted to determine the precise roles of FOXO1 and TCF1 in human engineered and non-engineered T cells during cancer immunotherapy." (PMID 38600391, 2024). "However, low dose of perifosine (50 nM) did not affect cancer cell proliferation and the phosphorylation status of AKT, FOXO1, and GSK-3β." (PMID 31113933, 2019). "However, in some other cancer cell types, in which FOXO1 does not regulate MDM2 transcription but instead activates CDKN1B transcription, FOXO1 may paradoxically act in a cancer-suppressing manner." (PMID 38519029, 2024).
infection (64 papers, 2009 to 2026). The state of being infected such as from the introduction of a foreign agent such as serum, vaccine, antigenic substance or organism. "Next, FoxO1 and FoxO3 deficient cells were infected at high and low MOIs, and virus replication was monitored through the time course of infection." (PMID 36016282, 2022). "Deletion of FoxO1 after the clearance of an infection resulted in a rapid loss of typical gene expression patterns in memory T cells." (PMID 36233176, 2022). "Examples are given with an emphasis on lineage specific deletion of Foxo1 to explore the impact of FOXO1 on cell behavior, inflammation and susceptibility to infection." (PMID 31849924, 2019). "Infection also induces loss of another essential DZ regulator, FOXO1, in bulk sequencing studies." (PMID 38059622, 2024). "FOXO1 inhibition in SARS-CoV-2-infected NHBE cells significantly reduced viral spike RNA levels 24 h post-infection." (PMID 41931532, 2026). "Conversely, FOXO3a and FOXO1 were exported from the host cell nucleus upon T. gondii-infection (respectively) in an MOI-dependent fashion (respectively)." (PMID 41450565, 2025). "In response to an infection, transcription factors such as fork-head box protein O1 (FOXO1) and nuclear factor of activated T cells, cytoplasmic 1 (NFATC1) upregulate the expression of PD-1 on antigen-activated T cells as they eliminate the pathogen." (PMID 39339217, 2024). "Inactivation of FoxO1 leads to the reversion of memory T cells to a state of terminal differentiation, which prevents a secondary memory response in multiple cases of infection." (PMID 36233176, 2022). "The transcriptome analysis showed an increase in FoxO1 and FoxO3 mRNAs early in infection (4 h.p.i.), however, the results were somewhat inconclusive for the FoxO4 transcript due to the low number of the reads (not shown)." (PMID 36016282, 2022). "Our siRNA results suggested a more pronounced requirement for FoxO3a than FoxO1 during HCMV lytic infection, echoing the role we found for FoxO3a in HCMV reactivation from latency in the THP-1 model and in CD34+ human progenitor cells (HPCs)." (PMID 35946797, 2022). "It is possible that a similar mechanism is involved in response to infection, and FOXO1 plays a protective role in this." (PMID 35844510, 2022). "Similar effects on FOXO1 phosphorylation were also observed following infection of HUVEC with adenovirus expressing myr-Akt." (PMID 34381074, 2021). "Studies have shown that AKT3 induced by IAV can inhibit FoxO1, and the FoxO pathway can inhibit IAVs infection by mediating anti-apoptosis and anti-inflammatory reaction." (PMID 34867371, 2021). "We previously reported that forced FOXO1 activation in glomerular cells by infection with lentiviral vectors protected the mesangial cells and podocytes in the kidneys of streptozotocin-induced diabetic animals." (PMID 30962862, 2019). "FOXO1 KO increased the ROS accumulation under HG condition, whereas this effect was greatly reduced by infection with si-TX." (PMID 30962862, 2019). "We found that inhibition of FOXO1 by AS1842856 allows the efficient infection of resting T cells by HIV-1." (PMID 31042779, 2019). "It is therefore possible that the effect of IL-7 in resting T cell infection relates to this inhibition of FOXO1, but this requires further exploration." (PMID 31042779, 2019). "We reiterate the observation of dramatically higher levels of pFOXO1 in DPG3 infection induced MDDSCs compared to control monocytes suggesting that FOXO1 expression is negatively regulated by PI3K–AKT signaling pathway." (PMID 30413788, 2018). "This restores FOXO1 activity and establishes a positive feedback loop whereby FOXO1-driven Ang2 expression promotes microvascular leak during infection." (PMID 29740443, 2018). "At day 3 in the TA and SOL muscles, infection triggered increases in the mRNA expression of several autophagy-related genes, including Lc3b, Gabarapl1, Bnip3, Parkin, Lamp2a, and Foxo1." (PMID 28659735, 2017).